BRCA1 (BRCA1 DNA repair associated)
Diseases named in the same sentence as BRCA1 in open-access papers (continued):
Sharing a sentence is not in itself a finding about the gene and the disease.
breast cancer (continued). "While many mechanisms remain elusive, taken together, it is evident that BRCA1 has a crucial function, both directly and indirectly, in regulating EMT in breast cancer cells." (PMID 35008272, 2021). "Intriguingly, pro-tumorigenic roles of IQGAP1 were observed in breast cancer; its cytosolic and nuclear expressions, where IQGAP1 was co-localized with BRCA1, were detected in triple negative breast cancer." (PMID 33498739, 2021). "Pan-HDAC inhibitors panobinostat and vorinostat hyperacetylate nuclear HSP90, resulting in proteasomal degradation of DNA repair machinery proteins BRCA1, ATR, and CHK1 in breast cancer cells." (PMID 34696786, 2021). "In total, 1,402 BRCA1 and 647 BRCA2 heterozygotes were diagnosed with a metachronous contralateral breast cancer before enrollment in CIMBA." (PMID 34113011, 2021). "By using our previously published resource of 43 invasive human breast cancers and the RNA prepared from microdissected FFPE sections of tumors 20, we assessed BRCA1 and GATA3 mRNA levels in 9 ER-positive and 10 ER-negative samples." (PMID 34373738, 2021). "Recent case-control studies in Caucasian women have reported relative risks of breast cancer for the BRCA1 and BRCA2 genes of 5.9–10.6-fold and 3.3–5.9-fold, respectively, which were lower than the magnitude of breast cancer risks estimated in this study." (PMID 34606182, 2021). "It will be important to revisit predictors of survival for women with MRI-detected breast cancer and for women with stage I cancers in both BRCA2 and BRCA1 carriers." (PMID 33597716, 2021). "Additionally, migration of breast cancer cells in response to CM of ADSCs proved to be equivalent or slower for BRCA1/2 mutated versus nonmutated cancer cells and, with exception of angiopoietin-like 2, induced expression of adipokines showed no major difference." (PMID 34228231, 2021). "In this study, we found that UBE2W expression was closely related to the expression level of BRCA1/2 and 5 MMR genes in breast cancer." (PMID 33931024, 2021). "Characteristics of MDA-MB-436 (BRCA1 c.5277 + 1G > A) and HCC1937 (BRCA1 p.Gln1756.Profs*74) were compared to MDA-MB-231 and T47D BRCA1/2 wild-type breast cancer cell lines." (PMID 34228231, 2021). "Activation of the TGFβ pathway was shown to result in reduced expression of ATM, BRCA1 and BRCA2 in BRCA-proficient breast cancer cells, and of RAD51 in lung epithelial cells -resulting in suppression of DNA damage repair." (PMID 34871431, 2021). "There was higher expression of IL6, MCP1, BCL2, luminal cytokeratins, MUC1, BRCA1, BRCA2, CEA and CA 15-3 in older women with primary breast cancer compared to younger women." (PMID 34165702, 2021). "Methylation at many gene promoters has been reported to have independent prognostic value in breast cancer including HOXA11, ESR1 and PITX2, HOXD13 CDH22 BRCA1 and RASSF1." (PMID 33461604, 2021). "A detailed multi-omics assessment of BRCA1 and BRCA2 mutant mouse models of breast cancer revealed that this difference in sensitivity to immunotherapy is driven, at least in part, by the quality of the immune infiltrate." (PMID 34572943, 2021).
breast cancer (continued). "Additional xenograft experiments are required to investigate the role of WEHI-7326 in combination in other breast cancer subtypes such as ER + (with tamoxifen/fulvestrant or aromatase inhibitors) and HER-2 amplified (with Herceptin), but also in BRCA1 mutant BC (with PARP-inhibitor)." (PMID 33712556, 2021). "To examine the clinical relevance of ALC1 status in the context of HRD cancers, we next examined if expression levels of ALC1, BRCA1/2, or ATM influence breast cancer survival in human patients." (PMID 33333017, 2021). "Furthermore, with the discovery of two major breast cancer susceptibility genes, BRCA1 and BRCA2, in 1994 and 1995, respectively, the association between family history and the presence of inherited genetic events that predispose individuals to breast cancer development was confirmed." (PMID 34573353, 2021). "Although the results from these early-stage clinical trials seemed promising for individuals with TNBC BRCA1/2 mutant disease, the stage III clinical trial OlympiAD showed no benefit of adding PARPi to the standard of care for advanced breast cancers." (PMID 33470989, 2021). "Expression of other PARP genes was higher in somatic BRCA1 and BRCA2 carriers in breast cancer, and in gBRCA1, sBRCA1, and gBRCA2 in ovarian cancers." (PMID 33525353, 2021). "Similar to BRCA1, the potential application of NBR2 as a cancer biomarker was initially revealed in breast cancer, as the expression of NBR2 decreased in primary cancer cells derived from human breast cancer tissues." (PMID 34926299, 2021). "We also performed immunohistochemistry to assess BRCA1, PINK1, and Parkin expressions in breast cancer tissues derived from patients." (PMID 33888730, 2021). "EIF3E, another 8q-protein in the RRM2B network, interacts with ATM and BRCA1 for the execution of DNA damage response and EIF3E alterations have been previously observed in breast cancer." (PMID 33868369, 2021). "Pan-HDAC inhibitors panobinostat and vorinostat hyperacetylate nuclear HSP90, which degrades DNA repair machinery proteins BRCA1, ATR, and CHK1 in breast cancer cells." (PMID 34696786, 2021). "Several pathological CNVs, such as CNV of BRCA1, MTUS1 and hTERT, have been identified in the initiation and progression of breast cancer subtypes, suggesting a specific contribution of CNVs to breast cancer." (PMID 34364397, 2021). "BRCA1 has been shown to directly bind to the TWIST promoter, suppressing its activity and inhibiting EMT in mammary tumor cells." (PMID 35008272, 2021). "Current non-surgical measures of breast cancer prevention using tamoxifen or aromatase inhibitors rely on evidence gained from adjuvant treatment and offer poor protection against the triple-negative subtype typically associated with the BRCA1 mutation carrier state." (PMID 32120796, 2020). "BRCA1 c.4801A>T was recorded in Breast Cancer Information Core (BIC) in Chinese and appeared to be recurrent in one breast cancer and one cervical cancer patient in the present study (sample ID: 71, 78)." (PMID 32879886, 2020). "We have previously reported that BRCA1 restrains metabolic activity and proliferative response to IGF-I anabolic actions in breast cancer cells cultured in high glucose." (PMID 33212987, 2020). "BRCA1 and BRCA2 are two highly penetrant genes involved in the inherited breast cancer and contribute to different DNA damage pathways and cell cycle and apoptosis cascades." (PMID 33013205, 2020). "Moreover, miR-638 and miR-218 can target Breast Cancer 1 Gene (BRCA1) and interfere with tumor cells’ abilities to repair cisplatin-induced DNA damage, increasing the efficiency of platinum salts in BC." (PMID 32967267, 2020).
breast cancer (continued). "Abnormal expression of BRCA1, BRCA2, and PALB2 has been observed in about 10% of breast cancer cases." (PMID 32824813, 2020). "During the 25 year period since the BRCA1 and BRCA2 genes were identified, a number of additional breast cancer genes have been identified." (PMID 31963545, 2020). "Although identification of BRCA1 and BRCA2 has greatly increased the understanding in breast cancer genetics in Western populations but the role of these genes for developing breast cancer in the Bangladeshi population still remains unexplored." (PMID 32856854, 2020). "Genomic DNA was extracted from peripheral blood sample of a young woman affected with breast cancer belonging to a HBOC family and the entire coding regions of the BRCA1 and BRCA2 genes were amplified using the Ion AmpliSeq BRCA1 and BRCA2 Panel." (PMID 33159495, 2020). "Nonetheless, Asian populations are reporting higher detection rates of BRCA1/2 PV/LPV carriers; as high as 25% in Asian females with breast cancer." (PMID 33110458, 2020). "Susceptibility genes with high or moderate penetrance (i.e., BRCA1, BRCA2, PALB2, ATM, and CHEK2) have been identified in 30 to 40% of patients with a family history of breast cancer, but only in 5% of sporadic breast cancer cases." (PMID 33126731, 2020). "Because for them to come here, I don’t think so they would” – 49-year-old female, BRCA1 PV/LPV carrier, with breast cancer." (PMID 33110458, 2020). "In summary, our results indicate that BRCA1/ZBRK1 affects the transcriptional regulation of PFKP, providing important evidence for the understanding of abnormal mechanism of breast cancer glycolysis." (PMID 32470015, 2020). "We conclude that by modulating the cellular localization of BRCA1, PRMT1 is an important regulator of the oncogenic functions of BRCA1, contributing to the epigenetic defense of breast cancer cells against ionizing radiation." (PMID 32764667, 2020). "I think pictures or graphs help people to remember better” – 43-year-old female, BRCA1 PV/LPV carrier, with breast cancer." (PMID 33110458, 2020). "No Significant horizontal pleiotropy based on PRIVW method was observed in overall breast cancer and hereditary breast cancer in BCAC and BRCA1 carriers." (PMID 33167385, 2020). "The synergistic anti-tumor effect of combination PARPi and ATRi was demonstrated in PARPi-resistant BRCA1-mutant EOC models and breast cancer models." (PMID 32722408, 2020). "In both SOC (OV) and breast cancer (BRCA), the frequency of monoallelic deletions of either BECN1 or BRCA1 was >10-fold that of the frequency of single-nucleotide variant or insertion-deletion mutations." (PMID 31923184, 2020). "Analysis of the human breast cancer database revealed a close correlation between high expression levels of NOTCH1 and TNBC incidence, especially BRCA1-related TNBC." (PMID 32591500, 2020). "Interrogation of CCLE database revealed a positive correlation of FZD5 with FOXM1, BRCA1, and BIRC5, several key factors related to cell cycle, DNA replication, DNA damage repair, and survival, in a total of 57 breast cancer cell lines." (PMID 33311446, 2020).
breast cancer (continued). "The diagnosed population for BRCA1 mutation rate in TNBC breast cancer, including both germline and somatic mutation, is about 15–20%, which means approximately 80% of BRCA1‐proficient TNBC breast cancer patients could not benefit from PARP inhibitors treatment." (PMID 33231937, 2020). "The BRCA1 and BRCA2 genes are directly related to hereditary breast cancer, and are more frequently present in patients with a family history of breast cancer." (PMID 33257598, 2020). "BRCA1 and BRCA2 genes are currently proven to be closely related to high lifetime risks of breast cancer." (PMID 31998560, 2020). "BRCA1 and BRCA2 were silenced by promoter methylation in 9 and 2% of sporadic breast cancer respectively." (PMID 32974031, 2020). "BRCA1 and BRCA2 (breast cancer predisposition gene 1/2)are the strongest susceptibility genes for BCaccounting for up to half of the heritable mutations in BC and inherited in an autosomal dominant pattern with incomplete penetrance." (PMID 32102521, 2020). "The de-methylation of BRCA1 leading to the re-expression of protein and restored HR was demonstrated in patient-derived xenograft (PDX) models of PARPi-resistant breast cancer." (PMID 32722408, 2020). "BRCA1 and ERBB2, which play key roles in breast cancer, were significantly correlated with 60 and 43 ATG genes, respectively." (PMID 31896739, 2020). "A number of genes, such as p16, BRCA1, RASSF1A, APC, and GSTP1, are reported to be hypermethylated in breast cancer." (PMID 32992445, 2020). "Further, tamoxifen-resistant breast cancer cells express observably more BARD1 and BRCA1, lending chemoresistance to DNA-damaging therapy especially in ER-positive breast cancer patients." (PMID 32528278, 2020). "Tumor suppressor genes like p16, BRCA1, GSTP1, TIMP-4, and CDH1 contribute to breast cancer progression and growth." (PMID 32824813, 2020). "The digitalMLPA is a fast and reliable method to detect copy number changes in relevant regions for BRCA1- and BRCA2-like classification in one experiment in breast cancer samples." (PMID 32711554, 2020). "Mutation in the BRCT domain disturbs the proper connection between BRCA1 and BACH1, which results in delayed entry into the S phase of the cell cycle, defective DNA repair, and breast cancer development." (PMID 33013205, 2020). "A subsequent study utilised skin biopsies of 30 (10 BRCA1, 10 BRCA2 and 10 sporadic) women with a history of breast cancer who were disease free at time of recruitment." (PMID 33081408, 2020). "After the introduction of PARP (polyadenosine diphosphate ribose polymerase) inhibitors as a therapy of choice for BRCA1/2-related HBOC, the differentiation between genetic and sporadic breast cancer became increasingly important." (PMID 32727387, 2020). "BRCA1 and BRCA2 are the most commonly tested genes in individuals presenting with early-onset breast cancer, triple-negative breast cancer, bilateral breast cancer and familial breast/ovarian cancer." (PMID 32468491, 2020). "The decrease in BRCA1 gene promoter methylation and expression by genistein in breast cancer cells was also attributed to a decrease in DNMT1 expression both in vitro (MCF7, UACC3199, and HCC38 cell lines) and in vivo (BRCA1 F22/24 mice)." (PMID 32878338, 2020). "BRCA1 and BRCA2 are two highly penetrant genes involved in inherited breast cancer and contribute to different DNA damage pathways and cell cycle and apoptosis cascades." (PMID 33013205, 2020).
breast cancer (continued). "We successfully amplified and sequenced the exons of BRCA1 and BRCA2 in seventy breast cases with breast cancer and/or ovarian cancer family history, and a total of 48 variants were detected in discovery stage." (PMID 32879886, 2020). "More than 70% of breast cancers exhibit promoter hypermethylation in at least one among a panel of four genes (GSTP1, BRCA1, CDH1, p16)." (PMID 32069786, 2020). "Of course, it is necessary to indicate that BRCA1/2-mutant patients in this study are derived from the gene mutations detection of TCGA cancer patients, who are not distinguished between somatic mutations and germline mutations (not necessarily as hereditary breast cancer patients)." (PMID 31998560, 2020). "Tamoxifen-resistant breast cancer cells are resistant to cisplatin and ADR because of high BRCA1 expression." (PMID 33311446, 2020). "Tamoxifen-resistant breast cancer cells highly overexpress BARD1 and BRCA1, resulting in chemoresistance to DNA-damaging therapies including cisplatin and doxorubicin, but not to paclitaxel." (PMID 32528278, 2020). "We found that circIQCH sponges miR-145 and promotes breast cancer progression by upregulating DNMT3A and downregulating PTEN and BRCA1." (PMID 32756009, 2020). "Previous population studies have identified several BRCA1/2 pathogenic mutations in Caucasians, for example, BRCA1 c.68_69del, BRCA1 c.5266dup, and BRCA2 c.5946del were the most frequent variants and could greatly increase the cumulative risk of breast cancer during a woman's lifetime." (PMID 32879886, 2020). "Depletion of the HR proteins BRCA1/2, PALB2, ABRAXAS, and BARD1 in MCF7 breast cancer cells was shown to elicit synthetic lethal interactions with PARG depletion or PARG inhibition (with gallotannin or PDD00017273)." (PMID 32029455, 2020). "As PFKP was regulated by BRCA1/ZBRK1 axis, we next explored what the role of PFKP in cell growth and colony formation in breast cancer cells MDA-MB-231." (PMID 32470015, 2020). "BRCA1 carriers at the 5th and 95th percentiles of the PRSER- distribution were predicted to have breast cancer risks to age 80 years of 59% and 83%, respectively." (PMID 32665703, 2020). "A trend of an increasing number of driver alterations of breast cancer-related genes was observed in recurrence samples as compared to primary tumors, including alterations in FGFR1, ESR1, NF1, BRCA1, and PTEN genes." (PMID 33059724, 2020). "In addition, researchers reported that approximately 40% of women with pathogenic BRCA1 mutation and approximately 26% of women with pathogenic BRCA2 mutation develop secondary breast cancer in the contralateral 20 years after the first diagnosis of breast cancer." (PMID 33488844, 2020). "The primary screen focused on 74 genes previously shown to be synthetic lethal with olaparib in BRCA1 and BRCA2-proficient MCF7 breast cancer cells." (PMID 30889383, 2019). "The significant contribution of additional genes, other than BRCA1 and BRCA2, was also observed in breast cancer patients." (PMID 31159747, 2019). "In estrogen-positive receptor breast cancer cells (the characteristic of MCF7 cells), cytosolic BRCA1 expression is inversely related to survival." (PMID 32010625, 2019). "While the loss or reduced expression of nuclear BRCA1 is prevalent in basal-like breast cancers with negative estrogen, progesterone, and epidermal growth factor receptors (triple negative), its cytosolic expression is observed in estrogen-positive receptor breast cancers." (PMID 32010625, 2019).